GPR68 (G protein-coupled receptor 68)
Diseases named in the same sentence as GPR68 in open-access papers (continued):
Sharing a sentence is not in itself a finding about the gene and the disease.
cancer (continued). "Tumors of the thyroid gland, the stomach or the esophagus showed increased or decreased expression of GPR68 depending on the type of cancer." (PMID 33113952, 2020). "GPR68 presents a widespread pattern of expression in normal human tissues while the analysis of public RNA sequencing data of 45 different types of cancer reveals a significantly differential expression in more than 70% of these tumors." (PMID 33113952, 2020). "The upregulation of these receptors on cancer cells has been suggested as a potential drug target in various cancers—such as GPR68 in head and neck squamous cell cancers, wherein it mediates acid-induced cellular responses including proliferation, invasion, and drug resistance." (PMID 41375084, 2025). "For instance, GPR68 expression in pheochromocytoma and cervical adenocarcinoma was shown to be positively correlated with patient survival, suggesting its value in diagnosing these cancers." (PMID 41190345, 2025). "Thus, GPR68 can have pro- or anti-tumorigenic functions, which are dependent on the cancer cell type and context." (PMID 39336742, 2024). "Although others have primarily characterized the role of GPR68 in cancer associated fibroblasts, we hypothesize that in GBM, GPR68 mediates pro-survival mechanisms triggered by the acidic TME." (PMID 38291540, 2024). "Here, using a murine model of chemical-induced OED, we showed that GPR68-deficiency increases the incidence of severe dysplasia and SCC, suggesting that endogenous GPR68 may attenuate cancer progression." (PMID 36611126, 2023). "GPR68 potentiation may provide one potential anti-cancer strategy and will be important to assess in a future study." (PMID 36611126, 2023). "Some studies suggest that the expression of GPR68 in cancer cells reduce their malignancy." (PMID 33113952, 2020). "All these results suggest that GPR68 may play beneficial or deleterious effects on cancer progression depending on the kind of cells in which is expressed." (PMID 33113952, 2020). "For example, the g-protein coupled receptor (GPCR) GPR68 has recently been identified as a novel sensor of fluid flow necessary for vascular physiology, and may be an emerging therapeutic target in cancer." (PMID 32503141, 2020). "GPR68 signaling pathways have been identified in several human cancers." (PMID 30696114, 2019). "Such compounds, we believe, may be candidates as anti-cancer therapeutics, especially for tumors in which GPR68 enhances their growth or metastatic potential." (PMID 30696114, 2019). "In addition to its functions in normal physiology emerging evidence implicates GPR68 as playing key roles in human cancer." (PMID 30696114, 2019). "GPR68 expression is highly upregulated in numerous types of cancer." (PMID 30696114, 2019). "In this review, we focus on GPR68 and its emerging role in human cancers." (PMID 30696114, 2019). "Examples highlighting this complexity include pro-inflammatory signaling downstream of GPR68 in intestinal epithelium, anti-fibrotic effects of GPR68 activation in stromal fibroblasts, and pro-survival ATF4 signaling in cancer cells." (PMID 41595528, 2026). "Based on our findings, we propose that small molecule GPR68 inhibitors like OGM, which selectively induce ferroptosis in GBM cells, represents a promising therapeutic avenue for this deadly cancer." (PMID 38291540, 2024). "GPR68 overexpression has also been shown to inhibit cell proliferation and increase apoptosis in HEY and MCF7 cancer cells." (PMID 39336742, 2024). "The knockdown of GPR68 or the inhibition of IL-6/STAT3 pathway in MSCs suppress in situ tumor growth and prolong lifespan after cancer grafting." (PMID 34681692, 2021). "A decrease in extracellular pH promotes growth, migration, invasion, and metastasis of cancer cells in an acidic environment via GPR4, GPR65 (TDAG8), GPR68 (OGR1), and GPR132 (G2A), which are pH-sensing G protein-coupled receptors (GPCRs)." (PMID 32998265, 2020).
cancer (continued). "Recent studies show that the pH-sensing GPCRs, including GPR4, GPR65 (TDAG8), GPR68 (OGR1), and GPR132 (G2A), regulate cancer cell metastasis and proliferation, immune cell function, inflammation, and blood vessel formation." (PMID 24367336, 2013). "It has been suggested that highly expressed GPCRs in cancer cells (e.g., GPRC5A in PDAC and colon cancer cells and GPR68 in PDAC CAF) may contribute to malignant phenotypes and may be novel therapeutic targets for cancer as biomarkers." (PMID 35885996, 2022). "EVs exclusively contained PLEKHG2 (nucleotide-binding protein), GPR68 (a proton sensing G protein-coupled receptor 68), POU4F2, ADAMTS9, and Let-7 microRNA precursor, which are involved in cell development, signal transduction, and cancer metastasis." (PMID 35663013, 2022). "Most mechanistic work has been carried out in non-OA systems such as intestine, lung, bone, and cancer models, but collectively these studies provide a framework for how GPR68 could integrate acidic and inflammatory cues across joint compartments." (PMID 41595528, 2026). "By contrast, evidence for GPR68 function in other joint compartments, including synovium, endothelium, and sensory neurons, is limited and largely inferred from studies in non-joint tissues such as intestine, lung, vasculature, and cancer models." (PMID 41595528, 2026). "Although clinical evidence that GPR68-mediated signaling may have a predictive role in cancer immunotherapy is lacking, the latter considerations may provide an interpretive key to our results." (PMID 40061137, 2025). "Importantly, since the GPR68-mediated pro-survival mechanism is activated only in the setting of the acidic milieu of cancers, noncancerous tissues should not be affected, as evidenced by the lack of cell death caused by OGM in fibroblasts and normal neural tissue." (PMID 38291540, 2024).
inflammation (6 papers, 2016 to 2025). Aberrant reaction of the microcirculation characterized by movement of fluid and leukocytes from the blood into extravascular tissues. "In this study, we found that high-GPR68-expressing monocytes infiltrated into the heart ventricle of 5/6Nx mice and they played an essential role in the exacerbation of cardiac inflammation and fibrosis." (PMID 33986294, 2021). "Moreover, Gpr68 inhibition in monocytes alleviates CKD induced cardiac inflammation." (PMID 36400753, 2022).
cardiac disease (3 papers, 2021 to 2025). "The ARNTL-mediated induction of monocyte GPR68 expression may be involved in systemic inflammation, serving as a potential risk factor for cardiac disease during CKD." (PMID 39684718, 2024). "A search for the underlying cause of the attenuation of heart disorder in Clk/Clk mice with 5/6 nephrectomy (5/6Nx) led to identification of the monocytic expression of G protein-coupled receptor 68 (GPR68) as a risk factor of CKD-induced inflammation and fibrosis of heart." (PMID 33986294, 2021). "Moreover, activation of GPR68 promoted inflammation and fibrosis of the heart, which suggests that GPR68 is a potential player in the occurrence and progression of heart disease, and its high expression may be associated with poor prognosis." (PMID 41190345, 2025). "The expression of G-protein-coupled receptor 68 (GPR68), which exacerbates CKD-induced cardiac disease, was regulated by ARNTL." (PMID 39684718, 2024).
infection (2 papers, 2023 to 2024). The state of being infected such as from the introduction of a foreign agent such as serum, vaccine, antigenic substance or organism. "Clock genes in monocytes may play an important role in biological defense by generating circadian rhythms in infection and innate immune responses via GPR68." (PMID 39684718, 2024).
nervous system diseases (2 papers, 2019 to 2020). "Furthermore, the osteocrin-derived peptide 128 (Osteocrin33-50) shares disease associations with GPR68, spanning cardiovascular, eye, genetic, immune system, metabolic, and nervous system diseases." (PMID 31675498, 2019). "Since persistent acidosis is prevalent in disease conditions while GPR68 do not exhibit rapid desensitization, GPR68-dependent mechanisms arguably would have close relevance to long-term psychophysiological changes commonly seen in various neurological diseases." (PMID 32993733, 2020).
cardiovascular disorder (1 paper, 2024). A disease involving the cardiovascular system. "Because the expression of GPR68 and ARNTL in monocytes in patients with CKD correlates with renal function, targeting these molecules in monocytes/macrophages could offer potential therapeutic strategies for treating CKD-induced cardiovascular disorders." (PMID 39684718, 2024).
GPR68 also shares sentences with these, for which no sentence is quoted: Adenocarcinoma of the (3 papers); fibrosis (3); ischemia (3); allergic asthma (2); cervical adenocarcinoma (2); dermatofibrosarcoma protuberans (2); endometrial cancer (2); eosinophilia (2); gastrointestinal stromal tumor (2); lung (2); lung adenocarcinoma (2); lymphoma (2); medullary thyroid carcinomas (2); neuropathies (2); osteoporosis (2); pancreatic adenocarcinoma (2); peripheral neuropathy (2); Allergy (1); Alzheimer disease (1); Autoimmunity (1); basal cell carcinoma (1); blood cancer (1); brain edema (1); breast adenocarcinoma (1); carcinoids (1); cerebral infarction (1); Cerebral ischemia (1); cervical cancer (1); chronic kidney failure (1); colorectal adenocarcinoma (1).
A further 30 diseases each share a sentence with GPR68 in 1 paper.